NOP53 (NOP53 ribosome biogenesis factor)
Description:
Nucleolar protein which is involved in the integration of the 5S RNP into the ribosomal large subunit during ribosome biogenesis. In ribosome biogenesis, may also play a role in rRNA transcription. Originally identified as a tumor suppressor, it may also play a role in cell proliferation and apoptosis by positively regulating the stability of PTEN, thereby antagonizing the PI3K-AKT/PKB signaling pathway. May also inhibit cell proliferation and increase apoptosis through its interaction with NF2. May negatively regulate NPM1 by regulating its nucleoplasmic localization, oligomerization and ubiquitin-mediated proteasomal degradation. Thereby, may prevent NPM1 interaction with MYC and negatively regulate transcription mediated by the MYC-NPM1 complex. May also regulate cellular aerobic respiration. In the cellular response to viral infection, may play a role in the attenuation of interferon-beta through the inhibition of RIGI.
Synonyms: PICT-1; GLTSCR2; PICT1
Tractability: Small molecule: a structure with a bound ligand is known. PROTAC: ubiquitination databases record sites on it.
Gene: Protein-coding gene on chromosome 19 (47,745,520 to 47,757,058, forward strand). Ensembl gene ENSG00000105373.
Subcellular location: Nucleus, nucleolus; Nucleus, nucleoplasm
Subcellular location (Human Protein Atlas): Nucleoli
Gene Ontology:
Molecular function: 5S rRNA binding; identical protein binding; protein binding; RNA binding
Biological process: cellular response to hypoxia; DNA damage response; DNA repair; mitotic G2 DNA damage checkpoint signaling; negative regulation of phosphatidylinositol 3-kinase/protein kinase B signal transduction; negative regulation of proteasomal ubiquitin-dependent protein catabolic process; negative regulation of protein-containing complex assembly; negative regulation of transcription by RNA polymerase II; negative regulation of transcription of nucleolar large rRNA by RNA polymerase I; positive regulation of proteasomal ubiquitin-dependent protein catabolic process; positive regulation of protein K63-linked deubiquitination; protein localization to nucleoplasm; protein stabilization; regulation of aerobic respiration; regulation of apoptotic process; regulation of cell cycle; regulation of protein phosphorylation; regulation of RIG-I signaling pathway; ribosomal large subunit assembly; protein localization to nucleolus
Cellular component: cytosol; fibrillar center; nucleolus; nucleoplasm; rDNA heterochromatin
Genetic constraint (gnomAD): Loss-of-function variants: 35 observed, 43.03 expected, observed/expected ratio (o/e) 0.81, 90% interval 0.62 to 1.08. The synonymous counts are far from expectation, so gnomAD's model fits this gene poorly and the ratio says little. Missense variants: 601 observed, 506.4 expected, observed/expected ratio (o/e) 1.19, 90% interval 1.11 to 1.27. Synonymous variants: 278 observed, 217.29 expected, observed/expected ratio (o/e) 1.28, 90% interval 1.16 to 1.41.
Homologues: Orthologues: chimpanzee NOP53 (99% identical), macaque NOP53 (97% identical), chimpanzee NOP53 (92% identical), pig NOP53 (83% identical), guinea pig NOP53 (82% identical), mouse Nop53 (82% identical), rat Nop53 (81% identical), dog NOP53 (66% identical), tropical clawed frog nop53 (49% identical), zebrafish nop53 (48% identical), Drosophila melanogaster CG1785 (27% identical), Caenorhabditis elegans Y39B6A.33 (23% identical).
Diseases named in the same sentence as NOP53 in open-access papers:
NOP53 is named in the same sentence as 30 diseases in open-access papers, as found by Europe PMC text mining. Sharing a sentence is not in itself a finding about the gene and the disease. The quoted sentences say what the papers report.
glioma (6 papers, 2012 to 2023). A benign or malignant brain and spinal cord tumor that arises from glial cells (astrocytes, oligodendrocytes, ependymal cells).
viral infection (4 papers, 2016 to 2025). "NOP53 is involved in regulating the RLR signaling pathway during viral infection, providing insight into the mechanism of RLR-mediated antiviral responses." (PMID 29677136, 2018). "NOP53 is a tumor suppressor protein that translocates to the cytoplasm during viral infection." (PMID 38228690, 2024).
ovarian carcinoma (2 papers, 2014 to 2020). A malignant neoplasm originating from the surface ovarian epithelium. "We have experimentally probed that HMGB1, HMGB2 and two of their partners, MIEN1 and NOP53 are also involved in the response of ovarian cancer cells to several drugs used in chemotherapy against EOC." (PMID 32867128, 2020). "Expression changes of HMGB1, HMGB2, MIEN1 and NOP53 genes have been evaluated in response to drugs usually employed in ovarian cancer treatments: bevacizumab, olaparib, paclitaxel or carboplatin." (PMID 32867128, 2020). "With these precedents we decided to investigate the role of HMGB1, HMGB2, MIEN1 and NOP53 in cell viability as well as in response and sensitivity to drugs currently used in ovarian cancer therapy." (PMID 32867128, 2020). "Interestingly, we have shown in our study that HMGB1, HMGB2 and their EOC-HMGB-interactome partners MIEN1 and NOP53 are involved in the response to carboplatin, or drugs nowadays used in ovarian cancer treatment, such as bevacizumab, olaparib and paclitaxel." (PMID 32867128, 2020). "HMGB1 and HMGB2 genes were silenced in SKOV-3 and PEO1 EOC cell lines and levels of mRNA from 4 detected interacting partners of HMGB1 or HMGB2 in ovary cancer, COMMD1, MIEN1, NOP53 and ZNF428, were analyzed by qRT-PCR as explained in Materials and Methods." (PMID 32867128, 2020). "We tested the effect of four compounds, used in ovary-cancer therapy in the expression of the genes HMGB1, HMGB2, MIEN1 and NOP53 in cultured cancerous SKOV-3 cells and in non-cancerous IOSE-80 ovarian cells." (PMID 32867128, 2020).
brain tumor (1 paper, 2020). "NOP53, considered a tumor suppressor in brain tumor cells, is overexpressed after treatment with paclitaxel and bevacizumab, and NOP53 silencing decrease sensitivity to bevacizumab in SKOV-3 cells." (PMID 32867128, 2020). "NOP53 had been identified as a tumor suppressor downregulated in brain tumor cells; however, in other cancers (esophagus or colon), NOP53 behaves as an oncogene that increments its expression in malignant cells." (PMID 32867128, 2020).
follicular carcinomas (1 paper, 2019). "Interestingly, it has already been reported that NOP53 (GLTSCR2) had higher expression in aggressive follicular carcinomas than in non-aggressive ones." (PMID 31703244, 2019).
seminoma (1 paper, 2023). A radiosensitive malignant germ cell tumor found in the testis (especially undescended), and extragonadal sites (anterior mediastinum and pineal gland). "Moreover, seminoma displayed high expression of genes associated with innate immune response, regulation of B cell activation (e.g., CCL5, APOE, MIF, NOP53), suggesting that the immune activity in TME play a role in tumorigenesis." (PMID 38123589, 2023).
tumor (23 papers, 2009 to 2024). "Immunohistochemistry exhibited increased NOP53 protein expression in tumor samples from affected family members, compared with normal adjacent thyroid tissue." (PMID 31703244, 2019). "The nucleolar protein NOP53 (also designated PICT-1/GLTSCR2) is a tumor suppressor." (PMID 29677136, 2018).
cancer (13 papers, 2009 to 2022). A tumor composed of atypical neoplastic, often pleomorphic cells that invade other tissues. "Whether NOP53 is a suppressor or enhancer of cancer malignancy remains controversial." (PMID 36316314, 2022).
infection (5 papers, 2016 to 2022). The state of being infected such as from the introduction of a foreign agent such as serum, vaccine, antigenic substance or organism. "NOP53 is a tumor suppressor protein located in the nucleolus and is translocated to the cytoplasm during infection by vesicular stomatitis virus (VSV) and herpes simplex virus type 1 (HSV-1), as shown in our previous study." (PMID 29677136, 2018). "We found that NOP53 is expressed as a set of discrete globular structures within the nuclei of different types of cell lines, consistent with previous work;41 then migrated from the nuclei upon infection at 12 h.p.i." (PMID 29367603, 2018).
NOP53 also shares sentences with these, for which no sentence is quoted: gastric cancer (2 papers); glioblastoma (2); lung carcinoma (2); non-small cell lung carcinoma (2); squamous cell carcinoma (2); acute megakaryoblastic leukemia (1); adenocarcinoma (1); Anal atresia (1); benign tumors (1); breast carcinoma (1); cervical cancer (1); colorectal tumors (1); emphysema (1); Esophageal atresia (1); esophageal cancer (1); esophageal tumors (1); hepatocellular carcinoma (1); neuroblastoma (1); skin cancer (1); Tracheoesophageal fistula (1); uterus cancer (1).